DHRS9 (dehydrogenase/reductase 9)
Description:
3-alpha-hydroxysteroid dehydrogenase that converts 3-alpha-tetrahydroprogesterone (allopregnanolone) to dihydroxyprogesterone and 3-alpha-androstanediol to dihydroxyprogesterone. Also plays a role in the biosynthesis of retinoic acid from retinaldehyde. Can utilize both NADH and NADPH.
Synonyms: 3-alpha-HSD; RDH-TBE; RDH15; SDR9C4; RDHL; 3alpha-HSD; RETSDR8; RDHTBE; hRoDH-E2
Tractability: Antibody: UniProt predicts a signal peptide or a membrane-spanning region. PROTAC: its protein half-life has been measured.
Target class: Enzyme; Oxidoreductase
Gene: Protein-coding gene on chromosome 2 (169,064,789 to 169,096,168, forward strand). Ensembl gene ENSG00000073737.
Subcellular location: Microsome membrane; Endoplasmic reticulum membrane
Pathways (Reactome):
Sensory Perception: The canonical retinoid cycle in rods (twilight vision)
Signal Transduction: RA biosynthesis pathway
Gene Ontology:
Molecular function: alcohol dehydrogenase (NAD+) activity; all-trans-retinol dehydrogenase (NAD+) activity; androstan-3-alpha,17-beta-diol dehydrogenase (NAD+) activity; androsterone dehydrogenase [NAD(P)+] activity; testosterone dehydrogenase (NAD+) activity; racemase and epimerase activity; 17-beta-hydroxysteroid dehydrogenase (NAD+) activity; oxidoreductase activity, acting on the CH-OH group of donors, NAD or NADP as acceptor
Biological process: 9-cis-retinoic acid biosynthetic process; androgen metabolic process; progesterone metabolic process; epithelial cell differentiation; retinol metabolic process; retinoic acid biosynthetic process
Cellular component: endoplasmic reticulum membrane
Genetic constraint (gnomAD): Loss-of-function variants: 18 observed, 28.08 expected, observed/expected ratio (o/e) 0.64, 90% interval 0.44 to 0.95. The upper end of that interval is the gene's LOEUF score, 0.95, which puts it in group 4 of 6, group 1 being the genes least tolerant of losing a copy. Missense variants: 425 observed, 399.94 expected, observed/expected ratio (o/e) 1.06, 90% interval 0.98 to 1.15. Synonymous variants: 134 observed, 149.44 expected, observed/expected ratio (o/e) 0.9, 90% interval 0.78 to 1.03.
Homologues: Orthologues: chimpanzee DHRS9 (99% identical), macaque DHRS9 (97% identical), dog DHRS9 (89% identical), pig DHRS9 (88% identical), guinea pig DHRS9 (87% identical), mouse Dhrs9 (86% identical), rat Dhrs9 (86% identical), rabbit DHRS9 (81% identical), tropical clawed frog dhrs9 (58% identical), zebrafish dhrs9 (47% identical). Paralogues in human: RDH16 (47% identical), HSD17B6 (45% identical), RDH5 (44% identical), SDR9C7 (43% identical), BDH1 (33% identical), HSD17B2 (30% identical), HSD11B2 (29% identical), RDH10 (23% identical), HSD17B1 (23% identical), RDH12 (22% identical), SDR16C5 (22% identical), RDH11 (22% identical), and 13 more.